IKBIP (IKBKB interacting protein)
Diseases named in the same sentence as IKBIP in open-access papers (continued):
Sharing a sentence is not in itself a finding about the gene and the disease.
tumor (continued). "This study examined the immunological status of patients with cancer and discovered a connection between IKBIP and tumor immune cells by measuring IKBIP expression." (PMID 36999060, 2023). "To confirm that the tumor-promoting effect of IKBIP was achieved by the activation of the AKT pathway, we used LY294002 (10 μg/mL), a specific inhibitor of the PI3K/AKT signaling pathway, to treat KYSE-150 cells with IKBIP overexpression (OE) and their matched control cells (Vector)." (PMID 38914958, 2024). "Furthermore, we detected the expression of the IKBIP protein in 126 ESCC tumor tissues and 108 matched adjacent normal tissues through IHC staining assay." (PMID 38914958, 2024). "By searching the UALCAN database, we found the expression of IKBIP increased with tumor stage, N stage and tumor differentiation grade, indicating that IKBIP may become a new biomarker for ESCC prognosis." (PMID 38914958, 2024). "Additionally, we evaluated the expression of IKBIP in patients with different cancer stages (stage 1–4), N stages (stage N0-N3) and tumor differentiation grades (stage 1–3) through the UALCAN database." (PMID 38914958, 2024). "IHC analysis of isolated tumor tissues revealed that the expression of Ki-67 in the tumor tissues of the IKBIP-overexpressing group was significantly greater than that in the corresponding control group, indicating that IKBIP plays a tumor-promoting role in ESCC progression in vivo." (PMID 38914958, 2024). "IKBIP plays a tumor-promoting role in ESCC and may serve as a predictive biomarker and a potential therapeutic target for ESCC." (PMID 38914958, 2024). "After normalizing the raw expression matrices, we performed differential expression analysis of the IKBIP gene in tumor tissues and paired normal tissues and found that IKBIP expression was significantly upregulated in both ESCC (p < 0.001) and ESCA (p < 0.01) tissues." (PMID 38914958, 2024). "It should be emphasized that the role of IKBIP in different tumors may vary depending on the tumor tissue type, tumor microenvironment, and position in the gene regulatory network." (PMID 38914958, 2024). "We studied whether there is a link between IKBIP and immune-related genes, microsatellite instability (MSI), and the incidence of tumor mutational burden (TMB)." (PMID 36999060, 2023). "We hypothesized that high IKBIP expression and high TMB and MSI expression predict improved prognosis and responsiveness to ICI treatment in tumor types where IKBIP expression is positively linked with TMB." (PMID 36999060, 2023). "Based on these results, we speculate that PI3K/AKT signaling inhibitors may be effective at inhibiting tumor development in ESCC patients with high IKBIP expression but may be ineffective at preventing tumor development in ESCC patients with low IKBIP expression." (PMID 38914958, 2024). "To explore the protein expression of IKBIP in ESCC tissues, we performed IHC staining on 126 ESCC tissues and 108 adjacent non-tumor tissues." (PMID 38914958, 2024). "Knockdown of IKBIP significantly inhibited the proliferation, survival, and migration of ESCC cells and inhibited tumor growth in xenograft nude mice." (PMID 38914958, 2024). "The IKBIP protein was stained brown and was mainly located in the cytoplasm of ESCC tumor cells; the nuclei were stained blue (magnification: 100× and 400×)." (PMID 38914958, 2024). "These 6 tumor-exclusive proteins detected in every single sample comprised MARCKSL1, IKBIP, COPZ1, TIMP1, FAM50A and DPM3." (PMID 39681068, 2024). "The results showed that among the tumor-related pathways, the PI3K/AKT signaling pathway was clustered, indicating that IKBIP was likely involved in the activation of this signaling pathway." (PMID 38914958, 2024). "Based on these results, we demonstrated that IKBIP expression was significantly upregulated in ESCC tissues and was closely related to the clinical stage, tumor stage and overall survival of patients with ESCC." (PMID 38914958, 2024).
tumor (continued). "The results showed that the IKBIP gene was hypomethylated in ESCA tissues, which may lead to the upregulation of IKBIP expression in tumor tissues." (PMID 38914958, 2024). "IKBIP was variably expressed in tumor and non-tumoral tissues, as well as during various stages of tumor development, according to our analysis of IKBIP expression across all cancer types." (PMID 36999060, 2023). "The function of IKBIP and its effects on the tumor immune microenvironment have not been fully investigated." (PMID 36999060, 2023). "To further verify whether IKBIP promotes ESCC development in vivo, we constructed tumor cell-derived xenograft models (NC, sh-1, Vector and OE) by subcutaneously injecting 1 × 106 KYSE-150 cells transfected with pLV-NC, pLV-IKBIP-sh1, pCDH-Vector or pCDH-IKBIP into the right axilla of nude mice." (PMID 38914958, 2024). "IFNGR2, KLF10, PLAUR, MSN, and IKBIP, whose coefficients of risk score were >0, had positive correlations with risk score, stromal score, immune score, and ESTIMATE score and negative relationships with tumor purity." (PMID 38137116, 2023).
cancer (5 papers, 2021 to 2024). A tumor composed of atypical neoplastic, often pleomorphic cells that invade other tissues. "In several cancer types, IKBIP expression has been linked to immune invasion and immunological checkpoint markers." (PMID 36999060, 2023). "We also investigated the latent association between genetic changes in IKBIP and patient prognosis for various cancer types." (PMID 36999060, 2023). "Third, although the results of the pan-cancer analysis showed that IKBIP expression was linked to immune cell infiltration and immunomodulatory mechanisms, further research is needed to determine the underlying mechanism." (PMID 36999060, 2023). "In 13 pan-cancer subtypes, IKBIP expression was linked to TMB levels." (PMID 36999060, 2023). "IKBIP is associated with patient staging and prognosis in some cancer types, suggesting that IKBIP may have the potential to be a prognostic marker." (PMID 36999060, 2023). "Additionally, IKBIP is associated with numerous immunological and cancer-promoting pathways." (PMID 36999060, 2023). "Furthermore, IKBIP expression was linked to TMB in 13 cancers and MSI in seven cancers." (PMID 36999060, 2023). "A. The UALCAN database showed the expression of IKBIP in different individual cancer stages (stages 1–4) in ESCA." (PMID 38914958, 2024). "The various expression levels were linked to various clinical outcomes, which calls for more research into the precise function of IKBIP in each cancer type." (PMID 36999060, 2023). "As the role of drug resistance in cancer has been gaining attention, we further investigated the analysis of potential correlations between drug sensitivity and IKBIP expression using the CellMinerTM database." (PMID 36999060, 2023). "We used TCGA data for pan-cancer transcriptome analysis and found that IKBIP expression was positively correlated with the matrix scores of PAAD, BRCA, COAD, READ, ESCA, and BLCA." (PMID 36999060, 2023). "We thoroughly investigated the predictive importance of IKBIP in pan-cancer, clinical traits, and genetic anomalies." (PMID 36999060, 2023). "We also investigated pan-cancer alterations in IKBIP using the cBioPortal (TCGA Pan-Cancer Atlas) database." (PMID 36999060, 2023). "ICGs are a practical measure of the effectiveness of immunotherapy; hence, we conducted a correlation analysis between the expression of ICGs and IKBIP in different pan-cancer subtypes." (PMID 36999060, 2023). "The mRNA expression of IKBIP was analyzed using multiple cancer databases." (PMID 38914958, 2024). "Because of the one-of-a-kind dynamics that exist between IKBIP and the immune response, we used the TIMER database to carry out an in-depth investigation into the connection between the level of IKBIP expression and the extent to which immune cells are present in different types of cancer." (PMID 36999060, 2023). "IKBIP transcription varies significantly among various cancer stages in these malignancies." (PMID 36999060, 2023). "In conclusion, IKBIP is differentially expressed and highly sensitive and specific in some cancers, suggesting that IKBIP may play a potentially critical role in cancer diagnosis." (PMID 36999060, 2023). "In cancer, kappa B-interacting protein (IKBIP) has rarely been reported." (PMID 33552590, 2021). "Here, we examined the correlations between IKBIP expression and MSI in datasets related to all types of cancer." (PMID 36999060, 2023). "DNA methylation provides a potential biomarker for the early diagnosis and prognosis of cancer, but there is a lack of studies on IKBIP methylation." (PMID 36999060, 2023). "IKBIP has a significant relationship with the infiltration of B cells, CD8+ T cells, CD4+ T cells, macrophages, neutrophils, and dendritic cells (DC) across a wide range of cancers." (PMID 36999060, 2023).
cancer (continued). "Overall, these results suggest that IKBIP expression is correlated with TMB, MSI, ICGs, and TME in multiple pan-cancer datasets, convincingly indicating that it could be a robust and reliable biomarker for predicting the responses of cancer cells to immunotherapy." (PMID 36999060, 2023).
IKBIP also shares sentences with these, for which no sentence is quoted: esophageal squamous cell carcinoma (1 paper); mesothelioma (1); oral cancers (1); osteoporosis (1); overnutrition (1); renal cell carcinoma (1).